VSIG1 (V-set and immunoglobulin domain containing 1)
Synonyms: GPA34; MGC44287; 1700062D20Rik; dJ889N15.1
Tractability: Antibody: UniProt predicts a signal peptide or a membrane-spanning region; its Gene Ontology location is reachable by antibodies, with medium confidence.
Gene: Protein-coding gene on chromosome X (108,044,970 to 108,079,184, forward strand). Ensembl gene ENSG00000101842.
Subcellular location: Membrane
Subcellular location (Human Protein Atlas): Cytosol; Vesicles
Gene Ontology:
Molecular function: protein binding
Biological process: maintenance of gastrointestinal epithelium; epithelial cell morphogenesis
Cellular component: basolateral plasma membrane; membrane; plasma membrane
Homologues: Orthologues: chimpanzee VSIG1 (99% identical), macaque VSIG1 (96% identical), dog VSIG1 (73% identical), pig VSIG1 (73% identical), rat Vsig1 (72% identical), guinea pig VSIG1 (71% identical), rabbit VSIG1 (70% identical), mouse Vsig1 (70% identical), tropical clawed frog vsig1 (33% identical). Paralogues in human: IGSF11 (25% identical), ESAM (24% identical), VSIG2 (24% identical), CLMP (22% identical), GPA33 (20% identical), CXADR (20% identical), VSIG8 (18% identical), JAM3 (17% identical), F11R (16% identical), JAM2 (16% identical), MXRA8 (14% identical), MUC15 (11% identical), and 2 more.
Diseases named in the same sentence as VSIG1 in open-access papers:
VSIG1 is named in the same sentence as 14 diseases in open-access papers, as found by Europe PMC text mining. Sharing a sentence is not in itself a finding about the gene and the disease. The quoted sentences say what the papers report.
gastric cancer (7 papers, 2021 to 2026). A primary or metastatic malignant neoplasm involving the stomach. "In gastric cancer, VSIG1 expression consistently correlates with preserved glandular architecture and epithelial differentiation, whereas reduced or absent expression accompanies dedifferentiation and architectural disorganization." (PMID 41827800, 2026). "It is known that V-set and immunoglobulin domain containing 1 (VSIG1) is a cell-cell adhesion molecule that can serve as an indicator of better survival in patients with gastric cancer." (PMID 38928294, 2024). "Due to its abundant expression in the stomach, VSIG1 has been extensively studied in gastric cancers." (PMID 36189222, 2022). "In support of this, overexpression of VSIG1 diminished the proliferation and migration of multiple gastric cancer cell lines in vitro." (PMID 36189222, 2022). "The VSIG1 gene is expressed in the normal testis and stomach, as well as in esophageal, ovarian, and gastric cancers, the TEX13B that is expressed in the testis during spermatogonia." (PMID 34777475, 2021). "For this reason, VSIG1 might be expressed in all tumors with gastric or hepatoid-like features, including hepatocellular carcinoma with gastric phenotype and, conversely, gastric carcinoma with hepatoid phenotype." (PMID 37240039, 2023). "Furthermore, downregulation of VSIG1 was significantly correlated with poor overall survival and worse clinical outcome in gastric cancer patients, suggesting that VSIG1 may function as a tumor suppressor gene." (PMID 36189222, 2022). "V-set and Immunoglobulin domain containing 1 (VSIG1) is a cell–cell adhesion molecule which role in the genesis and evolution of gastric cancer (GC) is not understood." (PMID 36171238, 2022).
ovarian carcinoma (4 papers, 2011 to 2025). A malignant neoplasm originating from the surface ovarian epithelium. "VSIG1, a cell adhesion protein of the immunoglobulin superfamily, is preferentially expressed in gastric, testicular, esophageal, and ovarian cancers." (PMID 36895481, 2023). "VSIG1, a cell adhesion protein of the immunoglobulin superfamily, is preferentially expressed in stomach, testis, and certain gastric, esophageal and ovarian cancers." (PMID 21991385, 2011). "Loss of MPZL3 decreased homotypic adhesion between ovarian cancer cells but did not affect heterotypic cell adhesion to mesothelial cells, suggesting that MPZL3 shares functional similarities to junctional adhesion molecules such as VSIG1." (PMID 40631617, 2025). "VSIG1, also known as glycoprotein 34 (GPA34) and normally only significantly expressed in stomach and testis, is overexpressed in gastric, esophageal and ovarian cancers but reported not to be increased in colon cancers." (PMID 24533081, 2014).
colon cancer (3 papers, 2014 to 2023). "VSIG1 has been reported to be related to the metastatic behavior of various colon cancer cell types, and nuclear positivity of VSIG1 has been observed in all cases of distant metastasis of gastrointestinal stromal tumors." (PMID 36895481, 2023). "In addition, the GPA33 glycoprotein which is similar to VSIG1 is markedly increased in most colon cancers and has been used as a target for therapeutics." (PMID 24533081, 2014).
colorectal cancer (2 papers, 2023). A primary or metastatic malignant neoplasm that affects the colon or rectum. "The precancerous lesion of CC, the ‘HPV‐related HSIL cluster,’ highly expressed VSIG1, which is also a biomarker of colorectal cancer precursor lesions." (PMID 36967539, 2023). "This fact is also sustained by VSIG1 negativity in colorectal carcinomas, except those with serrated pathways." (PMID 37240039, 2023).
hepatocellular carcinoma (2 papers, 2022 to 2023). A malignant tumor that arises from hepatocytes. "Cytoplasmic granular/dot-like VSIG1 immunostaining was firstly proved by our team, during a Romanian-Japan interdisciplinary research project, in normal hepatocytes and a histologic subtype of hepatocellular carcinoma (HCC) which was called by the researchers as “gastric-type HCC”18." (PMID 36171238, 2022).
adenoma (1 paper, 2014). A neoplasm arising from the epithelium. "Marked increased expression of MUC17, the cell junction protein genes VSIG1 and GJB5, and the antiapoptotic gene REG4 were found in SSA/Ps, relative to controls and adenomas, were verified by qPCR analysis of additional SSA/Ps (n = 21) and adenomas (n = 10)." (PMID 24533081, 2014).
lymph node metastases (1 paper, 2023). "The loss of VSIG1 indicates a risk for lymph node metastases." (PMID 37240039, 2023). "Clinicopathological features and immunophenotype of VSIG1: A statistically significant correlation was demonstrated between VSIG1 expression and Dukes-MAC-like stage: locally advanced cases with lymph node metastases tended to exhibit VSIG1 negativity." (PMID 37240039, 2023).
mucinous tumors (1 paper, 2021). "This process involves the increased expression of certain stomach‐restricted genes such as Hnf4α, Vsig1, Gkn3, Ctse and Onecut2 in Nanog‐deleted mucinous tumors." (PMID 33439550, 2021).
cancer (7 papers, 2022 to 2024). A tumor composed of atypical neoplastic, often pleomorphic cells that invade other tissues. "In GC, VSIG1 can be considered an indicator of gastric phenotype carcinomas, where carcinogenesis is mainly driven by MUC5AC." (PMID 37240039, 2023). "Earlier studies suggest that the levels of VSIG1 have been implicated in pro-metastatic and EMT: its reduced expression correlates with a poor prognosis and differentiation of certain cancer types." (PMID 35892586, 2022). "V-Set and Immunoglobulin Domain Containing 1 (VSIG1) protein is a recently discovered member of the junctional adhesion family and has been widely dysregulated in human cancer." (PMID 35892586, 2022). "Due the similarities between VSIG1 patterns of cytoplasmic expression in gastric- and hepatoid type carcinomas, it is, in our opinion, highly probable to exist a molecular linkage from developmental perspective between those two tumors." (PMID 36171238, 2022). "Overall, although the function of VSIG1 in modulating antitumor immune responses has not been explored thus far, given its importance as a cell surface tumor suppressor in contraining tumor growth and metastasis, targeting VSIG1 would be of great value for the treatment of different types of cancer." (PMID 36189222, 2022). "In 71 out of 217 HCCs (32.71%), simultaneous positivity for VSIG1 and TTF-1 was seen, being more specific for G1/G2 carcinomas with a trabecular architecture and a longer OS (p = 0.004)." (PMID 38928294, 2024). "It is not known why some carcinomas are not marked by VSIG1, although gastric mucosa express this protein, or why other tumors display a gastric immunophenotype." (PMID 37240039, 2023).
tumor (6 papers, 2022 to 2026). "The authors of these studies concluded that VSIG1 is a cell adhesion molecule which loss of expression in tumor cells is associated with a worse prognosis." (PMID 36171238, 2022). "The clinicopathological features of 94 GCs were examined in association with immunohistochemical (IHC) patterns of VSIG1, E-cadherin, and β-catenin which were assessed in the tumor core (central) vs. invasive edge." (PMID 36171238, 2022). "Since VSIG1 is known to function as a JAM involved in tight junction assembly, these data implicated a potential role of VSIG1 in modulating EMT during tumor metastasis." (PMID 36189222, 2022). "As well as emphasizing the association with a specific tumor phenotype, the loss of VSIG1 might indicate a tendency towards lymph node metastases." (PMID 37240039, 2023). "Mechanistically, VSIG1 maintains an immunosuppressive tumor environment through inhibiting the activation of CD8+ T cells and IL-11 secretion and other alternative mechanisms." (PMID 41150752, 2025). "The purpose of this study was to examine the potential prognostic role of VSIG1 in GC patients, based on its pattern of expression in the tumor core and the invasive edge, which is also known as the tumor invasion front." (PMID 36171238, 2022). "In conclusion, when located in the membrane of tumor cells, VSIG1 acts as an adhesion membrane protein, as it was previously highlighted." (PMID 36171238, 2022). "These patterns support interpretation of VSIG1 as a context-dependent indicator of lineage engagement and differentiation state rather than tumor origin or aggressiveness." (PMID 41827800, 2026). "In such cases, even though not entirely specific for this tumor, VSIG1 and MUC5 were able to confirm the diagnosis." (PMID 37240039, 2023).
adenocarcinoma (1 paper, 2023). A common cancer characterized by the presence of malignant glandular cells. "Of the thirteen published studies related to this relatively recently identified molecule, only three were focused on GC, all of them certifying that most of the adenocarcinomas are marked by VSIG1 and its loss is a negative prognostic factor." (PMID 37240039, 2023).
VSIG1 also shares sentences with these, for which no sentence is quoted: gastrointestinal stromal tumor (1 paper); hyperplastic polyp (1); intraepithelial neoplasia (1).